RYR1 (ryanodine receptor 1)
Diseases named in the same sentence as RYR1 in open-access papers (continued):
Sharing a sentence is not in itself a finding about the gene and the disease.
myopathies (continued). "There are several mutations in various RyR1-protein interaction and post-translational modification sites that result in autosomal dominant and recessive myopathies." (PMID 27855725, 2016). "For example, null mutations in the RYR1 are associated with the arthrogryposis and fetal akinesia phenotype while missense mutations in RYR1 are associated with central core myopathy phenotype (allelic heterogeneity)." (PMID 26933539, 2015). "Typically the mutations found in patients with recessively inherited RYR1-myopathies are a combination of null mutation with a missense mutation, though two missense mutations can occur." (PMID 25476234, 2014). "Both patients with classical RTT had different heterozygous missense mutations in the RYR1 gene, a regulator of Ca2+ release, which is responsible for a number of clinical conditions, including a mild form of myopathy." (PMID 23468869, 2013). "Until recently, the majority of research on RYR1-related myopathies has focused on dominant mutations in RYR1 that lead to CCD and MHS phenotypes." (PMID 23919265, 2013). "In fact, NAC pre-treatment has recently been shown to reduce pathological oxidative stress in another myopathies due to selenoprotein N or RYR1 mutations." (PMID 24098483, 2013). "Overall, our findings represent a comprehensive analysis of genotype-phenotype associations in recessive RYR1-myopathies." (PMID 23919265, 2013). "The RYR1 gene was regarded as the best candidate as mutations within this gene are responsible for a growing number of myopathies as well as for malignant hyperthermia susceptibility." (PMID 23894444, 2013). "Whereas the incidence of SIM is relatively low (approximately 10%) among the millions of statin users, it is highly possible that those individuals exhibiting signs and symptoms of SIM are harboring an underlying RyR1 myopathy." (PMID 24004537, 2013). "At present our understanding of the link between RyR1 mutations and statin myopathies has been limited to in vitro work with muscle biopsies." (PMID 24004537, 2013). "In this study, we present a comprehensive genotype-phenotype analysis of RYR1 mutations from more than 100 cases of recessively inherited RYR1-related myopathies." (PMID 23919265, 2013). "Very interesting, however, is the observation that patients with MH who lack clinical myopathies are more likely to have mutations at the N-terminus of RYR1, whereas those with clinical myopathies are likely to have mutations at the C-terminus." (PMID 21798098, 2011). "Core myopathies are caused by mutations in the ryanodine receptor (RYR1), the calcium channel located at the T-tubule/sarcoplasmic reticulum border that is required for excitation-contraction coupling, and by mutations in Selenoprotein-N, a modifier of RYR1." (PMID 19197364, 2009). "The pattern of selective involvement on muscle imaging is similar to that observed in classic CCD caused by dominant RYR1 mutations, and distinct from the selective muscle involvement described in myopathies due to recessive mutations in the SEPN1 gene." (PMID 17631035, 2007). "This work provides the first atomic-level explanation for statin-induced myopathy and reveals why individuals with RyR1 gain-of-function variants—already known to be overrepresented among statin-intolerant patients—are particularly vulnerable to muscle toxicity." (PMID 41430740, 2025). "Also, endoplasmic reticulum (ER) stress has been observed in conjunction with loss of RyR1 and as an underlying mechanism in several myopathies, such as CIC." (PMID 40183240, 2025). "Congenital myopathies may result from impaired excitation-contraction coupling due to RYR1 mutations." (PMID 40268053, 2025). "To assess the transcriptional correlates of aberrant hypertrophic development associated with dysregulated Ca2+ release through C3636A RyR1, we used qPCR analysis to assess the mRNA levels of eighty-four genes implicated in skeletal muscle myogenesis and myopathy in EDL muscle." (PMID 38820626, 2024).
myopathies (continued). "Interestingly, our group has previously demonstrated that the resting myosin dynamics are altered in patients with RYR1 mutation-related myopathies." (PMID 38752835, 2024). "As an example, a PE3 strategy delivered by electroporation in cultured human myoblasts achieved an impressive 59% correction efficiency of the mutation T4709M in ryanodine receptor 1 (RYR1), which contributes to motor dysfunction and muscle weakness in RYR1-related myopathies." (PMID 38785523, 2024). "The RyR1 mutation T4706M is linked to a myopathy characterized by muscle weakness." (PMID 37670077, 2023). "Here, in the presence of myopathy‐related RYR1 mutations, we mainly observed three additional (Thr1309‐P, Ser1362‐P, and Lys1410‐Ac on the β/slow MyHC) and six missing (Lys35‐Ac, Lys663‐Ac, Lys763‐Ac, Lys1171‐Ac, Lys1360‐Ac, and Lys1733‐Ac on the type IIa MyHC) PTMs." (PMID 37602753, 2023). "Amino acid substitutions in RyR1 are responsible for myopathies causing skeletal muscle weakness." (PMID 38203604, 2023). "In this study, MYLPF was significantly reduced in skeletal muscle of RYR1 mutation-associated myopathies, which may be critical to explain the development of myopathies related to RYR1 mutation." (PMID 35692882, 2022). "Interestingly, heterozygous knockin of the disease-causing RyR1-I4895T variant in mice causes impaired voltage-dependent Ca2+ release from intracellular stores in addition to myopathy in skeletal muscles." (PMID 35001666, 2022). "Given the association between RyR1 dysfunction, myopathy, and statin‐induced Ca2+‐release, we hypothesised that statin‐induced RyR1 activation is a contributing factor to the muscle‐related side effects of patients prescribed statin treatment." (PMID 35703154, 2022). "There is little data on the prevalence of MHS and other RYR1 associated myopathies in Singapore6." (PMID 35361824, 2022). "On the basis of functional studies, distinct molecular mechanisms were proposed to explain how specific RYR1 mutations could result in core myopathies and/or in MH." (PMID 35428369, 2022). "MYLPF (AUC: 0.786) has good diagnostic efficacy against RYR1 mutation-associated myopathies." (PMID 35692882, 2022). "CCD is the most frequent core myopathy, and RYR1 mutations are found in >90% of patients." (PMID 35980353, 2022). "Recessive mutations in RYR1 represent the second genetic cause of MmD, a myopathy presenting numerous cores, visible as pale spots in oxidative stained muscle sections, sometimes with a moth-eaten appearance and gathered in a limited area on longitudinal section." (PMID 35980353, 2022). "Impacted by their good diagnostic properties in RYR1 mutation-associated myopathies, a hypothesis was proposed that MYH1, ATP2A1, TNNT3, and MYLPF are likely to serve as biomarkers for diagnosing RYR1 mutation-associated myopathies." (PMID 35692882, 2022). "The discovery of genes achieving specific expressions within skeletal muscle of RYR1 mutation-associated myopathies may contribute to the discovery of key targets in the pathogenesis of RYR1 mutation-associated myopathies." (PMID 35692882, 2022). "In addition, TNNT3 was significantly reduced in skeletal muscle of RYR1 mutation-associated myopathies and had a high diagnostic value for RYR1 mutation-associated myopathies (AUC: 0.840)." (PMID 35692882, 2022). "RYR1 is associated with several such myopathies, such as CCD, certain subtypes of MMD, and CFTD." (PMID 35361824, 2022). "That cerivastatin activates RyR1 most strongly supports the hypothesis that RyR1 activation is implicated in statin‐induced myopathy." (PMID 35703154, 2022). "Early detection and diagnosis of RYR1 mutation-associated myopathies may lead to more timely treatment of patients, which contributes to the management and preparation for malignant hyperthermia." (PMID 35692882, 2022). "Accordingly, it is helpful to seek biomarkers to diagnose RYR1 mutation-associated myopathies." (PMID 35692882, 2022).
myopathies (continued). "Mutations in RYR1 have been rarely identified in some other myopathies." (PMID 35980353, 2022). "Thus, the pathogenesis and pathologic process of RYR1 mutation-associated myopathies should be clarified and diagnosed as soon as possible." (PMID 35692882, 2022). "Four skeletal muscle tissue-specific genes were identified, including MYH1, TNNT3, MYLPF, and ATP2A1, as the potential biomarkers for diagnosing and treating RYR1 mutation-associated myopathies, which provided insights into the transcriptome-level development mechanism." (PMID 35692882, 2022). "It is a potential biomarker of RYR1 mutation-associated myopathies with diagnostic efficacy." (PMID 35692882, 2022). "Both dominant (or de novo) and recessive mutations have been reported in RYR1-related myopathies." (PMID 34768808, 2021). "Cores and mini‐cores are seen in patients with myopathies due to mutation of RyR1." (PMID 35174322, 2021). "The most common causative gene for core myopathies is RYR1 and less frequent one is SEPN1." (PMID 34170073, 2021). "The annotation in ClinVar database is not specific for a given phenotype; however, individuals with pathogenic or likely pathogenic variants linked to RYR1-associated myopathies are reported to be at risk for MH during general anesthesia and should avoid triggering anesthetics." (PMID 34462577, 2021). "Because abnormal muscle fibers are a common pathological phenotype of RyR1-associated myopathies, we determined whether there were morphological anomalies in the mutant fibers as they first differentiate in embryos." (PMID 31383689, 2019). "However, as genetic testing is expanding the range of RYR1 mutations in core myopathies, it is becoming clear that the pathogenic mechanism cannot be predicted purely by mutational position." (PMID 31874912, 2019). "We report the identification of four RYR1 variants in two Italian families: one with myopathy and variants c.4003C>T (p.R1335C) and c.7035C>A (p.S2345R), and another with CCD and variants c.9293G>T (p.S3098I) and c.14771_14772insTAGACAGGGTGTTGCTCTGTTGCCCTTCTT (p.F4924_V4925insRQGVALLPFF)." (PMID 31165076, 2019). "Several morphological phenotypes have been associated to RYR1-recessive myopathies." (PMID 30611313, 2019). "Interestingly, recent population studies have reported a link between statin‐induced myopathy and patients with RyR1 mutations that give rise to MH." (PMID 29278865, 2018). "The development of a new class of statin molecules with reduced interaction with RyR1 may therefore particularly benefit statin users who are susceptible to myopathy." (PMID 29278865, 2018). "Whether ER stress/UPR contributes RyR1 myopathies arising from RyR1 mutations at other locations in the RyR1 structure also requires further investigation." (PMID 28337975, 2017). "In the index patient a variant detected in a gene associated with core myopathies (RYR1) was initially taken to be disease-causative, given that accepted in silico criteria for protein damage were met and there was morphological evidence of core myopathy in her muscle biopsy." (PMID 27005958, 2016). "Especially challenging is to explain how both gain- and loss-of-function mutations in RYR1 lead to myopathies characterized by damage and destruction of mitochondria (that is, CCD and multi-minicore disease), formation of structural and contracture cores, and muscle weakness." (PMID 26075051, 2015). "Thus, in a large cohort of RYR1-associated myopathies, dominant mutations tended to be associated with milder phenotypes whereas recessively inherited cases had an earlier onset and a more severe course." (PMID 25476234, 2014). "Additional important observations include the identification of enrichment of missense mutations in specific locations associated with particular histopathologic subtypes of RYR1-related myopathy, suggesting that histological phenotype is at least partially determined by mutation position." (PMID 23919265, 2013).
myopathies (continued). "Our results demonstrate the feasibility of expressing a therapeutic protein from multiple fragments deliverable by AAV vectors, which could be relevant to many genetic diseases caused by loss-of-function mutations in extra-large genes, such as nemaline- or RYR1-related myopathies." (PMID 40493400, 2025). "The prime editing technology may be used to correct mutations causing RYR1-related myopathies." (PMID 38201236, 2023). "Interestingly, mice heterozygous for the gain-of-function RyR1 variant Ile4895Thr, which is associated with central core disease in humans, develop a slowly progressive myopathy with skeletal muscle weakness and age-dependent formation of cores in their muscle fibers." (PMID 35001666, 2022). "Finally, a third mouse model with an inducible muscle-specific deletion of one RYR1 allele, leading to a 50% reduction in protein expression levels, showed typical signs of a myopathy with features of CCD and DuCD, progressive muscle weakness, atrophy, and mitochondrial dysfunction." (PMID 35980353, 2022). "In addition, the diagnosis of RYR1 mutation-associated myopathies may be challenging and requires genetic analysis, clinical manifestations, and histopathological evidence." (PMID 35692882, 2022). "Many individuals with myopathy due to RYR1 variants may also have susceptibility to MH." (PMID 36360420, 2022). "However, diagnosis of RYR1 mutation-associated myopathies is delayed and challenging." (PMID 35692882, 2022). "P44 inherited both variants from their mother, who also presented myopathy and elevated serum creatine phosphokinase, while P45 inherited a missense pathogenic variant from their unaffected father, although parental mosaicism has recently been described in RYR1-related myopathies." (PMID 35628876, 2022). "Moreover, these are also the sites of RyR1-RM disease causing mutations, indicating that defective regulation of RyR1 by Ca2+ and ATP may be a component of the pathophysiology of this form of myopathy." (PMID 34809703, 2021). "These include RYR1-related myopathies (RYR1-RM) that typically have a static or slowly progressive course and thus result in substantial disease burden over an affected individual’s lifetime." (PMID 40846977, 2025). "The most common CMyo are RYR1-related myopathies (RYR1-RM), with an estimated incidence of 1:90,000 among children in a representative population in the United States." (PMID 40993798, 2025). "We previously reported pathological Ca2+ leak from SR microsomes isolated from patients with RyR1-related myopathies." (PMID 40243436, 2025). "Congenital myopathies with mislocalized nuclei include CNMs and are genetically heterogeneous diseases caused by mutations in at least seven genes (MTM1, DNM2, BIN1, RYR1, TTN, SPEG and ZAK), with MTM1, DNM2, BIN1 and RYR1 being the most frequently associated." (PMID 41459639, 2025). "Enhanced statin-induced myopathy of RyR1-TM mice is mitigated by treatment with the Rycal drug S107." (PMID 41392983, 2025). "Heterozygous Ryr1 I4895T mice (from now on referred to as IT mice) exhibit a mild myopathy characterized by diminished muscle performance and reduced Ca2+ transients amplitude in skeletal muscle fibers." (PMID 41373610, 2025). "The proprioceptive system is involved in maintaining spinal alignment and indeed, patients with recessive RYR1 myopathies often present several skeleton abnormalities from birth, as well as joint contractures." (PMID 41091627, 2025). "Here, we investigated muscle spindle structure and gait properties in transgenic mice carrying the compound heterozygous Ryr1 mutations RyR1p.Q1970fsX16+p.A4329D (referable as dHT) a model for recessive Ryr1 myopathies." (PMID 41091627, 2025). "This study examined the exercise capacity in individuals with RYR1-related myopathies during a cardiopulmonary exercise test." (PMID 40993798, 2025).
myopathies (continued). "The pronounced fasciculations, muscle atrophy, and pathological reflexes, as well as their asymmetric presentation, are atypical for the differential diagnosis of myopathies, particularly RYR1-related myopathies." (PMID 41180248, 2025). "Exercise capacity is diminished in adults and children with RYR1-related myopathies yet remains stable over six months." (PMID 40993798, 2025). "The most frequently implicated genes include NEB and ACTA1 in nemaline myopathies and RYR1 in core myopathies." (PMID 40525497, 2025). "Five synonymous NEB, RYR1, and TTN variants were found to impact on splicing in three families with NM, one family with core myopathy and one family with CNM, respectively." (PMID 38982518, 2024). "Mutations in RYR1 cause a variety of myopathies that are broadly referred to as RYR1-related myopathies." (PMID 39501809, 2024). "RYR1-related myopathies pose some difficulties for the development of such new techniques, due to the very large size of the gene and the presence of numerous variants that often occur only in a single family." (PMID 39409197, 2024). "These showed symmetric fat accumulation and atrophy with a pattern consistent with typical MRI features described for RYR1-related myopathies." (PMID 39409197, 2024). "With the aim of gathering proof-of-principle evidence in this sense, we used a large cohort of patients with different forms of RYR1-related myopathy (RYR1-RM) in order to develop a novel unsupervised cluster analysis method." (PMID 36833224, 2023). "Among these, RyR1-related myopathies are often classified according to their specific histological presentation." (PMID 37670077, 2023). "A phase I trial (NCT04141670) examining the therapeutic potential of S48168(ARM210) to modify RyR1 leakiness in RyR1-related myopathy is currently underway." (PMID 37892218, 2023). "In the case of RYR1-related myopathies, the RYR1 wild-type gene can be epigenetically silenced in heterozygous individuals." (PMID 37628614, 2023). "Major histopathological groups of RYR1-related myopathies include central core disease (CCD), multiminicore disease, core-rod myopathy, and centronuclear myopathy." (PMID 37670077, 2023). "RYR1-related myopathies (RYR1-RM) are variable in intensity and include a wide disease spectrum of appointed and emerging phenotypes related to dominant and recessive inheritance patterns." (PMID 37627391, 2023). "Thanks to advances in gene sequencing, RYR1-related myopathy (RYR1-RM) is now known to manifest itself in vastly heterogeneous forms, whose clinical interpretation is, therefore, highly challenging." (PMID 36833224, 2023). "Next generation sequencing has resulted in an explosion in the identification of new RYR1 variations, expanding the clinical phenotypes of RYR1- related myopathies recently." (PMID 35693006, 2022). "We used a candidate gene approach using RYR1 Sanger sequencing to screen a large cohort of core myopathy patients." (PMID 35428369, 2022). "On the other hand, these results also expand the spectrum of non‐core myopathies within the larger family of RYR1‐related myopathies." (PMID 35666680, 2022). "Clinical heterogeneity was noted between patients with dominant and recessive RYR1-related myopathies, and within patients with the same inheritance mode." (PMID 35693006, 2022). "Mutations or variants in RYR1 and CACNA1S genes have been found to be more frequent in statin myopathy patients than controls." (PMID 35955495, 2022). "We report a Korean with MH having multi-minicore myopathy functionally supported by ex vivo RYR1-mediated intracellular Ca2+ release testing in B lymphocytes." (PMID 36292611, 2022). "Further studies are needed to assess the efficacy of these compounds and utility of the biomarkers in the genetic context of RYR1-related myopathies." (PMID 35698232, 2022).